BDNF (brain derived neurotrophic factor)
Diseases named in the same sentence as BDNF in open-access papers (continued):
Sharing a sentence is not in itself a finding about the gene and the disease.
cervical carcinoma (10 papers, 2019 to 2024). A carcinoma arising from either the exocervical squamous epithelium or the endocervical glandular epithelium. "This suggests that TRKB can potentially increase VEGF expression in cervical cancer, considering the association between BDNF/TRKB activation and VEGF expression in other models." (PMID 37445902, 2023). "Activation of the ERK and AKT pathways by BDNF/TRKB signaling has been implicated in cervical cancer cell proliferation." (PMID 37445902, 2023). "In cervical cancer, BDNF/TrkB signalling is overexpressed, and associated with poor prognosis, invasion, migration and EMT." (PMID 32971738, 2020). "In addition, BDNF levels are positively associated with lymph node metastasis in cervical cancer patients." (PMID 31608227, 2019). "Samples from Loop Electrosurgical Excision Procedure (LEEP) for suspected cervical cancer were obtained, and immunohistochemistry was performed to evaluate BDNF and NGF expression." (PMID 37445902, 2023). "Neurotrophins, such as BDNF and NGF, are overexpressed in tumor cells in cervical cancer, and HIV infection is associated with the upregulation of neurotrophin expression." (PMID 37445902, 2023). "BDNF/TRKB signaling has been shown to induce EMT-related changes in cervical cancer cells, including the downregulation of E-cadherin (a cell adhesion molecule) and the upregulation of mesenchymal markers such as N-cadherin and vimentin." (PMID 37445902, 2023). "Upregulation of the BDNF/TrkB pathway has been found to promote epithelial–mesenchymal transition, migration, and invasion in cervical cancer." (PMID 37445902, 2023). "BDNF and TrkB expression is significantly elevated in various cancer cells, including cervical cancer, highlighting their potential as targets for therapeutic intervention to improve patient survival and develop new treatments for cervical cancer metastasis." (PMID 37445902, 2023). "In cervical cancer cell lines, BDNF/TRKB enhances cell proliferation by activating ERK and AKT signaling pathways." (PMID 37445902, 2023). "TrkB as well as BDNF have been reported to be overexpressed in various types of cancer, such as colorectal and cervical cancers, and BDNF/TrkB overexpression has been shown to confer a migratory phenotype and chemotherapy resistance to tumor cells." (PMID 31941116, 2020). "In cervical cancer cell lines, BDNF/TRKB increases cell proliferation, apparently involving ERK and AKT signaling pathways." (PMID 31608227, 2019). "Although the role of BDNF in the TIME of cervical cancer has not been investigated yet, this evidence may suggest the role of BDNF in modulating the immune response also in patients with cervical cancer." (PMID 37445902, 2023). "In the context of cervical cancer, BDNF/TRKB are perhaps the best studied NTs." (PMID 31608227, 2019). "Therefore, BDNF may also play a crucial role in the PNI of cervical cancer patients." (PMID 39061654, 2024). "High expression of BDNF is also positively correlated with advanced FIGO stage, lymph node metastasis, and a poor prognosis in cervical cancer patients." (PMID 39061654, 2024). "Our results show that BDNF can play a key role as a link between the pathways by which HIV and HPV interact to accelerate cervical cancer progression and invasion." (PMID 37445902, 2023). "BDNF can play a key role as a link between the pathways by which HIV and HPV interact to accelerate cervical cancer progression and invasion." (PMID 37445902, 2023). "BDNF/TRKB signaling has been shown to induce the expression of vascular endothelial growth factor (VEGF), a key mediator of angiogenesis, in cervical cancer cells." (PMID 37445902, 2023). "Studies have demonstrated that BDNF and its receptor TRKB are overexpressed in cervical cancer tissues compared with normal tissues." (PMID 37445902, 2023). "miR-10a-5p can also inhibit the growth of cervical carcinoma cells while regulating and controlling the expression of the BDNF (brain derived neurotrophic factor) gene." (PMID 36578791, 2022).
cervical carcinoma (continued). "It has been described that BDNF and TRKB expression are significantly higher in cervical cancer tissues than in normal tissues and that their presence is higher in advanced stages of this neoplasm." (PMID 31608227, 2019). "Although there is currently no direct evidence of BDNF involvement in the neural innervation or PNI of cervical cancer, experiments have indicated that BDNF can enhance the motility and anoikis resistance of cervical cancer cells." (PMID 39061654, 2024). "The reprogramming-related genes, including transcription factors (CJUN), myelin genes (MBP), neurotrophic factors and receptors (BDNF, NGFR) and axonal regenerative marker (GAP43) were significantly elevated upon RSC96 cells co-cultured with cervical cancer cells." (PMID 39214988, 2024). "Currently, no data are available on the role of BDNF in the PNI of cervical cancer, especially in women with HIV infection." (PMID 37445902, 2023).
diabetic nephropathy (10 papers, 2015 to 2025). "Diabetic nephropathy is characterized by worsened nutritional deficiencies and heightened inflammation, which appear to go together with reduced BDNF-mediated support." (PMID 41142318, 2025). "Further investigation of the mechanisms underlying BDNF-associated diabetic nephropathy is needed." (PMID 25918454, 2015). "Intriguingly, enhanced BDNF mRNA expression and upregulated TrkB receptor levels have been reported in podocytes of patients with diabetic nephropathy, suggesting a possible compensatory or stress-response mechanism in hyperglycemic renal environments." (PMID 40791659, 2025). "Among the proposed mechanisms is the result of a defect in the lining of blood vessels and a decrease in the transfer of BDNF, since diabetic nephropathy is accompanied by damage to the microvasculature, which weakens the transfer of BDNF." (PMID 41142318, 2025). "It is particularly important to pay attention to maintaining optimal levels of BDNF to protect neurons from damage in patients with diabetic nephropathy." (PMID 41142318, 2025). "In diabetic nephropathy, this ongoing inflammatory milieu likely blunts BDNF production in the brain and throughout the body." (PMID 41142318, 2025). "Triptolide, a diterpenoid, prevents oxidative stress and inflammatory damage by upregulating brain-derived neurotrophic factor (BDNF) through downregulating miR-155-5p in a mouse model of diabetic nephropathy." (PMID 38805166, 2024). "BDNF is also localized in the processes and cell bodies of podocytes in patients with diabetic nephropathy." (PMID 35800175, 2022). "Several studies have focused on studying BDNF levels in patients with CKD due to diabetic nephropathy." (PMID 36362520, 2022). "In glomeruli of diabetic nephropathy patients, we found a strong BDNF signal in the remaining podocytes." (PMID 30133147, 2018). "BDNF may serve as a biomarker for diabetic kidney disease, highlighting the importance of nutritional status, inflammation control, and neurotrophic support." (PMID 41142318, 2025). "Low levels of BDNF in patients with diabetic nephropathy may be related to several mechanisms, including inflammation and oxidative stress, because some interleukins inhibit the production of this protein (such as IL-6 and IL-12)." (PMID 41142318, 2025). "In diabetic nephropathy, persistent high-glucose conditions may induce BDNF upregulation as an adaptive response, whereas the UUO model is more likely associated with fibrotic progression, oxidative stress, and mechanical injury that suppresses BDNF transcription." (PMID 40791659, 2025). "However, the effects of BDNF on diabetic nephropathy are unknown." (PMID 25918454, 2015). "In the current study, serum BDNF significantly decreased in diabetic nephropathy patients compared to diabetic patients without complications and the healthy control group." (PMID 41142318, 2025). "On the other hand, down-regulation of active p-PI3K, p-Akt, and p-mTOR by ceramide, resveratrol, brain-derived neurotrophic factor (BDNF), or oleanolic acid stimulates protective autophagy in pathological disease models, such as myocardial hypertrophy, ischemic brain injury, or diabetic nephropathy." (PMID 31547619, 2019).
endometrial cancer (10 papers, 2013 to 2025). Primary or metastatic malignant neoplasm involving the endometrium (mucous membrane that lines the endometrial cavity). "In endometrial carcinoma, BDNF/TrkB-ERK was found to upregulate ETV5, which mediates the invasive phenotype of cancer cells." (PMID 36872348, 2023). "In uterine cancers, BDNF and TrkB protein levels have been shown to be elevated in endometrial cancer versus normal tissues, with elevated TrkB correlating with increased lymph node metastasis and lymphovascular space involvement." (PMID 36077609, 2022). "BDNF/TrkB signaling has directly been shown to promote epithelial-to-mesenchymal transition and to inhibit anoikis in endometrial carcinoma cells both in vitro and in vivo." (PMID 36077609, 2022). "In our previous study, we confirmed that stimulation with brain-derived neurotrophic factor (BDNF), a natural ligand for TrkB, enhances TrkB-mediated endometrial carcinoma cell survival." (PMID 24321270, 2013). "In the present study, we found that both BDNF and TrkB are over-expressed in human endometrial carcinoma specimens." (PMID 23936232, 2013). "In endometrial carcinoma, BDNF-TrkB upregulates ETV5 through ERK-MAPK signaling (lower)." (PMID 36872348, 2023). "Cell surface receptor tyrosine kinase (TrKB) and its ligand, brain-derived neurotrophic factor (BDNF), are upregulated in endometrial carcinoma in comparison to normal epithelial cells." (PMID 26356073, 2015). "Furthermore, in CRC, cervical cancer, and endometrial cancer, m6A/IGF2BP1-mediated mRNA stabilizations of DEAD-box helicase 27 (DDX27), BDNF, and SYVN1 are also vital for tumor cells to enhance epithelial–mesenchymal transition." (PMID 40584294, 2025). "The known role of the BDNF–TrkB–ERK1/2 axis on neuronal plasticity and organogenesis might be mediating pro-metastatic events in endometrial cancer and as consequence the decrease in the p-ERK levels would lead to a less aggressive phenotype." (PMID 29682175, 2018).
Glucose intolerance (10 papers, 2013 to 2024). Glucose intolerance (GI) can be defined as dysglycemia that comprises both prediabetes and diabetes. "Accordingly, selective deletion of Rai1 in BDNF+ neurons results in increased body weight, glucose intolerance, and decreased intrinsic excitability of PVNBDNF neurons." (PMID 38672441, 2024). "Mice with skeletal muscle-specific BDNF deletion showed significant glucose intolerance and reduced insulin secretion." (PMID 32327658, 2020). "In support, mice (Sim1-Cre:Bdnf lox/lox) with BDNF depletion in Sim1+ cells, which blanket the PVN and represent several molecularly defined neuronal subpopulations, exhibit hyperphagia, obesity, glucose intolerance, and hyperinsulinemia compared to control littermates fed a chow diet." (PMID 38672441, 2024).
Impaired glucose tolerance (10 papers, 2010 to 2025). An abnormal resistance to glucose, i.e., a reduction in the ability to maintain glucose levels in the blood stream within normal limits following oral or intravenous administration of glucose. "Our previous study found that high fat diet-fed mice with impaired glucose tolerance expressed lower level of BDNF mRNA in VMH." (PMID 34054732, 2021). "Our data demonstrate that hypothalamic gene transfer of BDNF prevents aging‐associated metabolic decline including weight gain, loss of BAT function, hepatic steatosis, and impaired glucose tolerance." (PMID 30585393, 2019). "Some authors observed that BDNF treatment of obese and diabetic animals has a positive effect on glucose and lipid metabolism, with one study demonstrating that subcutaneous administration of BDNF reduces food intake and ameliorates impaired glucose tolerance in diet-induced obese mice." (PMID 25587547, 2014).
infarct (10 papers, 2012 to 2025). "The cardiac infarct area to area at risk ratio was decreased by intra-myocardial BDNF injection in mice subjected to left coronary artery ligation." (PMID 32679912, 2020). "However, when they formulated BDNF to pass the blood–brain barrier, BDNF reduced the post‐CI infarct area and increased the rotarod test duration." (PMID 38520223, 2024). "Interestingly, brain derived neurotrophic factor (BDNF) has a cardioprotective role in the heart after infarction by preventing adverse remodeling, and acts on endothelial cells to promote neovascularization in response to hypoxic stimuli via the Akt pathway." (PMID 32587529, 2020). "It was demonstrated that single‐dose ICV BDNF administration before CI improved motor‐sensory, sensorimotor and vestibular motor functions but did not reduce the infarct volume." (PMID 38520223, 2024). "Even though DAEE increases the BDNF mRNA, this would not affect the infarction but rather improve the neurological function." (PMID 22606023, 2012).
Infertility (10 papers, 2012 to 2023). "The NTRK2 gene encodes the NTRK2 receptor for neurotrophin-4/5 and brain-derived neurotrophic factor leading to oocyte death in late adolescence, loss of follicular tissue and infertility in early adulthood." (PMID 32252625, 2020). "BDNF has also been associated with different causes of infertility during in vitro fertilization." (PMID 36978655, 2023). "Abnormalities in the BDNF gene expression might be associated with the pathogenesis of male infertility disorders and the expression of BDNF in the semen sample of oligoasthenozoospermic men is lower than infertile men." (PMID 36381356, 2022). "Clarification of the mechanisms regulating the transcription of BDNF in the ovary will be helpful for improving the outcomes of infertility treatments." (PMID 34054723, 2021). "BDNF was originally discovered in the nervous system as a stress responsive messenger, but has recently shown to be related to human reproductive diseases including polycystic ovary syndrome, infertility, and impaired ovarian oocyte development." (PMID 32265693, 2020). "Brain-derived neurotrophic factor (BDNF), a member of the neurotrophin family, plays critical roles in the physiological process of oocyte mature and IVF outcomes of patients with infertility." (PMID 34054723, 2021). "BDNF in the FF plays an important role in the maturation of oocytes, fertilization, and early embryonic development, and this protein shows varying degrees of correlation with IVF outcomes in patients with different etiologies of infertility." (PMID 34054723, 2021).
Intraventricular hemorrhage (10 papers, 2018 to 2025). Bleeding into the ventricles of the brain. "Ventricular hemorrhage occurred, although it was limited to germinal matrix, and intraventricular hemorrhage can be associated with lower levels of BDNF." (PMID 35208502, 2022). "BDNF levels are higher in the third trimester of pregnancy and in neonates whose mothers received a complete course of antenatal steroids; conversely, low BDNF levels were associated with both chorioamnionitis and mild intraventricular hemorrhage (IVH)." (PMID 38534776, 2024). "Moreover, others also found that HUCB-MSCs and their secreted BDNF exert therapeutic effects in intraventricular hemorrhage and ameliorate neuronal loss and neurocognitive deficits via the BDNF-TrkB-CREB signaling pathway." (PMID 35769327, 2022). "Higher BDNF levels have been detected in the third trimester and in neonates whose mothers received a complete course of antenatal corticosteroids; conversely, low BDNF levels have been associated with chorioamnionitis and mild intraventricular hemorrhage (IVH)." (PMID 40943255, 2025). "Recent work has demonstrated the importance of BDNF secreted by MSC in brain neuroprotection after intraventricular hemorrhage in newborn rats." (PMID 34959314, 2021). "However, although the BDNF level was significantly increased with MSC transplantation compared to the intraventricular hemorrhage (IVH) control group, the absolute BDNF level was still much lower than that in the normal control group." (PMID 34768827, 2021).
malnutrition (10 papers, 2008 to 2025). Inadequate nutrition resulting from poor diet, malabsorption, or abnormal nutrient distribution. "Chronic energy deficiency, malnutrition, or conditions such as anorexia suppress BDNF and leptin signaling, resulting in decreased GnRH release and delayed or absent pubertal progression." (PMID 41614834, 2025). "In conclusion, low baseline BDNF levels were associated with malnutrition in CVD patients." (PMID 38319936, 2024). "Low baseline BDNF levels were associated with malnutrition in CVD patients." (PMID 38319936, 2024). "When taken together with our current findings, these results suggest that it is possible that malnutrition induces impaired skeletal muscle BDNF production and reduced serum BDNF levels." (PMID 38319936, 2024). "Malnutrition induced by low protein diet (PM) for 11 weeks or by food-added 0.4 g/kg MSG for 8 weeks into NF pups significantly lowered BDNF content in brain homogenate as revealed by ELISA analysis." (PMID 36015160, 2022). "Energy deficit, malnutrition, or leptin deficiency suppresses BDNF and kisspeptin expression, resulting in delayed or absent pubertal progression." (PMID 41614834, 2025). "In summary, the present data show that mild prenatalprotein malnutrition resulted in impaired ability of the EC to undergo LTP andto increase BDNF levels in response to tetanizing stimulation of theipsilateral ventral CA1 hippocampal region during postnatal life." (PMID 18604298, 2008).
memory (10 papers, 2017 to 2024). The activities involved in the mental information processing system that receives (registers), modifies, stores, and retrieves informational stimuli. "BDNF is one of the important regulators that underlies plasticity and can provide nutritional support for neurons and improve learning and memory impairment by reversing neuronal loss." (PMID 35130907, 2022). "Taking into account that the functional role of these molecules in regulating learning and memory, the activation of the ERK/CREB/BDNF signaling could account for the neuroprotective effects of GE on Scop -induced memory deficits." (PMID 30369882, 2018). "Our findings demonstrate that PS mitigates SCO-induced memory dysfunction by protecting synaptic integrity and activating the BDNF-ERK-CREB signaling pathway, indicating the potential of PS as a natural intervention for treating memory deficits." (PMID 39317682, 2024). "MK-801 antagonization of the NMDA receptor significantly increased CaMKII and CREB activation and BDNF expression in the DG, supporting the mechanistic involvement of NDMA receptor, CaMKII and CREB activation with BDNF expression in spatial learning and memory impairments of DIO rats." (PMID 38416255, 2024). "An altered ratio of pro‐BDNF/BDNF in favor of the pro‐form may lead to an enhancement of LTD and to a reduction of LTP in hippocampal neurons, with consequent synaptic dysfunction and memory deficits." (PMID 30403004, 2019). "Therefore, we investigated the use of a possible pharmacological approach intended to promote BDNF signaling in patients with DS and provide evidence that the treatment of Ts65Dn mice with the BDNF-mimetic drug 7,8-dihydroxyflavone (DHF), completely rescued learning and memory impairments." (PMID 29203796, 2017).